KRAS (KRas proto-oncogene, GTPase)
Diseases named in the same sentence as KRAS in open-access papers (continued):
Sharing a sentence is not in itself a finding about the gene and the disease.
colorectal cancer (continued). "Other literature gaps involve the treatment of colorectal cancer with HER-2 amplification and a KRAS G12C mutation with panKRAS inhibitors." (PMID 41301043, 2025). "Recent studies have uncovered the various roles of KRAS in colorectal cancer, highlighting its potential as a new therapeutic target." (PMID 39941797, 2025). "Recent breakthroughs in targeting the RAS oncogene began with KRAS-G12C inhibition, which has shown some promise in phase I/II clinical trials for metastatic lung, pancreatic, and colorectal carcinomas." (PMID 40896434, 2025). "Our findings identify a promising treatment option for pan-KRAS–mutant lung and colorectal carcinomas." (PMID 40091835, 2025). "As proof‐of‐concept, we demonstrate that the SmiRNP can deliver siRNA to silence KRAS in colorectal carcinoma cells, inducing cancer cell death in vitro and restraining tumor growth in vivo." (PMID 40702844, 2025). "We used immune-competent BALB/c mice that carried well-established, rapidly growing xenografts of a syngeneic CT26 (KRAS-mutant) colorectal carcinoma." (PMID 41465386, 2025). "By fusing a targeting module and an endosomal escape peptide onto the delivery platform, SmiRNP successfully delivered siRNA to silence the KRAS oncogene in a colorectal carcinoma cell line, leading to cancer cell growth suppression in vitro and in vivo." (PMID 40702844, 2025). "A clinical trial based on 76 colorectal cancer patients also confirmed that Adagrasib (an oral small molecule inhibitor of mutant KRAS G12C protein) had antitumor activity in patients with metastatic colorectal cancer." (PMID 39115621, 2024). "Colorectal cancer (CRC) is the second cause of cancer-related death; the CpG-island methylation pathway (CIMP) is associated with KRAS/BRAF mutations, two oncogenes rewiring cell metabolism, worse prognosis, and resistance to classical chemotherapies." (PMID 38540202, 2024). "In KRAS mutant colorectal cancer cell lines, a RAS-specific protease has been shown to induce irreversible growth arrest via p27." (PMID 38338768, 2024). "Hofmann and colleagues describe the mechanism underlying the therapeutic benefit of combinatorial use of SOS1 and KRAS-G12C inhibitors in the context of KRAS-G12C mutant-driven lung and colorectal cancer." (PMID 39103541, 2024). "Kirsten Rat Sarcoma Viral Oncogene Homolog (KRAS) gene variations are linked to the development of numerous cancers, including non-small cell lung cancer (NSCLC), colorectal cancer (CRC), and pancreatic ductal adenocarcinoma (PDAC)." (PMID 39001451, 2024). "Colorectal cancer (CRC) is the leading cancer among Saudis, and mutations in BRAF, KRAS, and NRAS genes are therapeutically significant due to their association with pathways critical for cell cycle regulation." (PMID 39635441, 2024). "Another G12C inhibitor, adagrasib (MRTX849), with demonstrated activity in KRAS G12C-mutated NSCLC and colorectal cancer (CRC), has recently shown effectiveness in PDAC and other solid tumors (NCT03785249)." (PMID 38610868, 2024). "Given their clinical relevance, the identification and understanding of KRAS and BRAF mutations have become crucial components of personalized medicine approaches in colorectal cancer." (PMID 39006576, 2024).
colorectal cancer (continued). "The combination of MTX-531 with mitogen-activated protein kinase kinase or KRAS-G12C inhibitors led to durable regressions of BRAF-mutant or KRAS-mutant colorectal cancer PDX models, resulting in striking increases in median survival." (PMID 38992135, 2024). "For example, combining cetuximab with RSL3 induced ferroptosis via suppressing the Nrf2/HO-1 signaling pathway in KRAS mutant colorectal cancer cells." (PMID 38347507, 2024). "For example, in KRAS-mutant colorectal cancer cells, the high expression of ASNS induced by PI3K-AKT-mTOR pathways leads to metabolic shifts that sustain tumor growth." (PMID 38474084, 2024). "This study’s finding supports previous research in which SOS1 degraders were deemed to be feasible therapeutic agents for KRAS-mutant colorectal cancer." (PMID 37641831, 2024). "In colorectal cancer (CRC), aberrations in KRAS are associated with aggressive tumorigenesis and an overall low survival rate because of chemoresistance and adverse effects." (PMID 38463818, 2024). "Importantly, the efficacy of BMS-986351 and cetuximab in colorectal cancer cell lines with KRAS mutations represents a potential treatment opportunity for cetuximab-resistant tumors, given that the mechanism of action of BMS-986351 may be independent of EGFR pathway activity." (PMID 38319147, 2024). "The pooled data suggest that while KRAS and BRAF mutations typically predict poorer outcomes in MSS colorectal cancer, their impact is less pronounced in MSI contexts, with implications varying across different stages of cancer and treatment responses." (PMID 38786299, 2024). "KRAS gene is involved in several cancers, namely lung cancer, colorectal cancer, pancreatic cancer, and ovarian cancer." (PMID 38170269, 2024). "In this study, we observed that this miRNA targets the rs712 region of KRAS, an SNV that has been associated with colorectal cancer, breast cancer, and breast cancer metastasis." (PMID 39057123, 2024). "Kirsten rat sarcoma viral oncogene homolog (KRAS) is a frequently mutated gene in various types of solid tumors, such as colorectal cancer, lung adenocarcinoma, and PDAC." (PMID 39501138, 2024). "CD19 was primarily targeted in ALL and NHL, while KRAS was frequently targeted in colorectal cancer." (PMID 39439803, 2024). "In particular, the frequencies of KRAS mutations are high in pancreatic ductal adenocarcinoma (PDAC; ~ 90%), colorectal cancer (CRC; ~ 45%), and non-small cell lung cancer (NSCLC; ~ 30%)." (PMID 38992694, 2024). "This evidence is counterintuitive as compared to prior studies in colorectal cancer, where MGMT methylation was associated with an increase of G‐to‐A KRAS point mutations." (PMID 39618336, 2024). "In contrast, Abdel‐Hafiz constructed a mouse colorectal cancer (CRC) model, and his research team found that cancer metastasis was higher and the prognosis was worse in male CRC mice carrying the oncogenic KRAS mutation (KRAS*) than that in females." (PMID 38222317, 2024). "Meanwhile APC shows a trend for PascalX (p-value 0.001 rank: 500 out of 18,874 protein coding genes) suggesting that APC inactivation can initiate oncogenesis earlier than KRAS activation in line with the current understanding of colorectal cancer oncogenesis." (PMID 39010058, 2024). "Combination therapies with allele‐specific covalent KRAS p.G12C inhibitors and anti‐EGFR targeted therapy have recently shown promising results in advanced colorectal cancer patients with KRAS c.34G>T (p.G12C) mutation." (PMID 39039804, 2024). "60% of endometrial cancer cases are co-mutated in KRAS and PI3KCA, yet only 7% of colorectal cancer patients exhibit these co-mutations." (PMID 39372214, 2024).
colorectal cancer (continued). "Kirsten rat sarcoma viral oncogene (KRAS) has also been suggested to play a central role in both the early phases of colorectal cancer’s malignant development and progressive metastatic illness." (PMID 39201782, 2024). "To investigate the relationship between ACSS2 expression and intracellular cholesterol levels in colorectal cancer, we measured cholesterol ester levels in KRAS mutant mouse colon epithelial cells." (PMID 38464238, 2024). "This review examines the landscape of KRAS inhibition in colorectal cancer (CRC), focusing on recent advances in therapeutic strategies targeting this oncogene." (PMID 39456549, 2024). "In PDAC, G12D mutant KRAS is considered to be a major driver in contrast to lung or colorectal cancer." (PMID 39687047, 2024). "LY3214996 proves effective in delaying or reversing resistance to BRAF and MEK inhibitors, and a synergistic effect was observed when combined with pan-RAF inhibitor LY3001920 in a KRAS-mutant colorectal cancer model." (PMID 38429288, 2024). "In our previous study, we determined vitamin C was able to induce HIF1a hydroxylation and degradation, downregulating GLUT1 and PDK1 in KRAS mutant colorectal cancer." (PMID 38425123, 2024). "In colorectal cancer, mutations in downstream molecules of EGFR, such as KRAS, NRAS or PI3K, can lead to a loss of response to anti-tumor drugs targeting EGFR and result in a poor prognosis for patients." (PMID 39000374, 2024). "We also tested two lines with distinct drug sensitivities based on alternative genomic contexts (one BRAF mutant melanoma (A375) sensitive to RAF inhibition and one KRAS wild type colorectal cancer (LIM1215) sensitive to EGFR inhibition)." (PMID 38822082, 2024). "The study employed the TruSight Tumor 15 next-generation sequencing (NGS) panel on 86 colorectal cancer (CRC) samples to detect somatic mutations in BRAF, KRAS, and NRAS genes." (PMID 39635441, 2024). "Previous studies have indicated that quercetin triggers apoptosis by activating the JNK pathway in KRAS-mutant colorectal cancer cells." (PMID 39519596, 2024). "Either way, it underscores that across KRAS-mutant model systems of pancreatic, lung, and colorectal cancer, resistance to dual-mechanism ERK/MAPK inhibition occurs secondary to large-scale transcriptional adaptations which rely on Mediator kinase." (PMID 38822082, 2024). "Lastly, cluster 5 concentrated on assessing the predictive value of KRAS and BRAF mutations within microsatellite-instability or microsatellite-stability subgroups in the context of colorectal cancer." (PMID 38706597, 2024). "This acts on the GTP-bound form of KRAS G12D, and has induced measurable responses in pre-clinical cell line derived mouse models of KRAS G12D mutated NSCLC and PDAC, although less so in colorectal cancer models." (PMID 39372214, 2024). "Previous studies have shown that it inhibits proliferation and invasion in cervical cancer by targeting specificity protein 1 (Sp1) and also inhibits colorectal cancer production by interacting with the KRAS/AKT/ERK pathway." (PMID 39595529, 2024). "These included four colorectal cancer patients (two with KRAS G12V, one with KRAS Q61L, one with NRAS G61K; patients #18, #28, #79 and #21) and one non-small cell lung cancer patient with no targetable mutations (patient #29)." (PMID 39138315, 2024). "These Amph vaccines have been implemented pancreatic and colorectal cancer, where neoantigens derived with KRAS G12D and G12R." (PMID 39066355, 2024). "The most notable interactions occur between CBD and EGFR, KRAS, BRAF, and MEK1, as reflected by docking scores and being the most critically mutated or dysregulated proteins in colorectal cancer." (PMID 39194723, 2024).
colorectal cancer (continued). "KRAS mutations are linked to the development of several carcinomas, including non-small cell lung cancer (NSCLC), colorectal cancer (CRC), and pancreatic ductal adenocarcinoma (PDAC)." (PMID 39001451, 2024). "When this drug was optimised for in vivo administration (BI-2493), tumour growth in colorectal cancer or PDAC cell line derived xenograft mouse models carrying KRAS G12C, G12D, G12V or A146V was slowed, and a tolerable toxicity profile seen." (PMID 39372214, 2024). "According to these findings, focusing on ATP7A is a method that can effectively eradicate colorectal cancer driven by the KRAS gene." (PMID 39408933, 2024). "KRAS can upregulate the expression of Jagged1, a ligand of the Notch pathway, and promote Notch signaling in colorectal cancer cells." (PMID 38481800, 2024). "Kristen rat sarcoma viral oncogene homolog (KRAS (HGNC ID: 6407)) is a gene that plays a significant role in cell signaling and is frequently mutated in various tumors, particularly colorectal cancer." (PMID 39673361, 2024). "Multiple driver genes of relatively high prevalence in other cancer types were associated with race, including an increased frequency of KRAS and PTEN mutations but decreased prevalence of APC and BRAF mutations in Black patients with colorectal cancer." (PMID 38297963, 2024). "As the most frequently mutated RAS gene (84%) in human cancer, KRAS mutations are associated with a worse prognosis in PDAC (90%), colorectal cancer (50%), non-small cell lung cancer (30%) and other human malignancies." (PMID 38409090, 2024). "The present study combines CIMP with additional tumor molecular biomarkers such as BRAF and KRAS for colorectal cancer diagnosis and prognosis prediction." (PMID 38681199, 2024). "This has been well demonstrated in a subset of lung, pancreatic, and colorectal cancer cell lines, which remain viable upon KRAS silencing." (PMID 39061234, 2024). "In contrast, PAK1, encoding the serine/threonine p21-activated kinase, plays a role in KRAS-driven colorectal cancer cell proliferation." (PMID 38213716, 2024). "This is supported by a previous article suggesting that KRAS and BRAF mutations with consequent activation of MEK1/2-ERK1/2 signaling increase the risk of lung metastasis in colorectal cancer patients." (PMID 38247543, 2024). "We first expanded upon the existing time-to-progression model by testing combined ERK and CDK8/19 inhibition across diverse KRAS-mutant pancreatic, lung, and colorectal cancer cell lines." (PMID 38822082, 2024). "EGFR and PI3K pathway signaling has also been implicated in the adaptive resistance of KRAS-mutant and BRAF-mutant colorectal cancer (CRC) to RAS–MAPK (mitogen-activated protein kinase) pathway intervention." (PMID 38992135, 2024). "In a phase 2 CodeBreaK100 trial, Sotorasib monotherapy showed only modest clinical activity in KRAS G12C mutant colorectal cancer with an objective response in only 6/62 (9.7%) cases." (PMID 38892436, 2024). "We visualized that scale expression of RGD-p21Ras-scFv entered KRAS wild and KRAS mutant colorectal cancer cell lines and co-localized with p21Ras protein by immunofluorescence." (PMID 38216883, 2024). "The anti-apoptotic protein B-cell lymphoma extra large (BCL-XL) is overexpressed in patients with KRAS/BRAF-mutant colorectal cancer." (PMID 38275900, 2024). "Patients with colorectal cancer had large frequency of variants in genes APC (50.2%), KRAS (23.2%), BRAF (14.6%), RNF43 (12.3%), and MSH3 (11.3%)." (PMID 39277826, 2024). "Genetic mutations are highly important in tumor progression, and mutations in KRAS and BRAF genes are key drivers in colorectal cancer." (PMID 39385899, 2024). "KRAS mutation is a critical genetic alteration with diagnostic value in various tumours, such as PC, LUAD and colorectal cancer." (PMID 38303549, 2024).
colorectal cancer (continued). "The results showed a significant difference between the control and cancer groups, indicating a difference in the KRAS gene pattern in gastric and colorectal cancer." (PMID 39673361, 2024). "PMC79 targets KRAS G12D and KRAS G12V and has been experimentally tested in colorectal cancer in vitro and in vivo." (PMID 38607041, 2024). "Evidence indicates that combinations of anti‐EGFR antibodies and KRAS p.G12C (c.34G>T) inhibitors can be an effective treatment strategy for advanced colorectal cancer." (PMID 39039804, 2024). "Consistent with the data obtained in vitro in human colorectal cancer cells, we observed a significant attenuation of the oncogenic KRAS activity, as evaluated by both WB on whole pancreas lysates and IHC with anti-pERK Ab." (PMID 39342278, 2024). "In contrast, we observed KRAS mutations to be enriched in B7-H3–high ovarian serous carcinomas (9.8% vs. 6.0%, q < 0.05) as well as MSS colorectal cancers (54.4% vs. 47.4%, q < 0.0001)." (PMID 38709075, 2024). "KRAS and BRAF mutations are important biomarkers in the management of colorectal cancer as they are not only predictive of response to anti-EGFR therapy but are also of prognostic value." (PMID 39364024, 2024). "Specifically, we demonstrated that in colorectal cancer cells exposed to fibroblast-derived factors, KRAS oncogenic signaling is predominantly governed by fibroblast-secreted factors." (PMID 39061234, 2024). "KRAS driver mutations, mostly occurred on 12th or 13th amino acid, which are commonly found in pancreatic ductal adenocarcinoma (PDAC) and colorectal cancer (CRC), present as attractive targets for immunotherapy." (PMID 39066355, 2024). "Compared to other KRAS-driven diseases like lung adenocarcinoma and colorectal cancer, pancreatic cancer has a higher prevalence of G12R, consistent with MAPK being the dominant signaling pathway driving pancreatic cancer." (PMID 38668053, 2024). "Apart from the stage of the tumor, new evidence confirms that people with colorectal cancer (CRC) who have stable microsatellites (MSS) and mutations in BRAF or KRAS genes tend to have worse survival rates." (PMID 39449806, 2024). "KRAS gene ctDNA detection in colorectal cancer patients; THMSas a molecular recognition probe; dual-enzyme cogroup amplificationof TdT and RNase HII; extraordinarily accurate and sensitive detection;detection limit of aM." (PMID 38950521, 2024). "Downstream of EGFR and KRAS, the protein kinase encoded by the V-Raf murine sarcoma viral oncogene homolog B1 (BRAF) gene is affected by mutations detected in 5–15% of colorectal cancer patients." (PMID 39722096, 2024). "We have previously shown that Homeodomain-Interacting Protein Kinase 2 (HIPK2) cooperates with KRAS in sustaining ERK1/2 phosphorylation in human colorectal cancers." (PMID 39342278, 2024). "A natural form of VC (L-VC) has been actively studied in the previous studies and only a few reports show a potent cytotoxic effect of L-VC or D-VC in combination with ATO in HCT116 (KRAS mutant) colorectal cancer cells including tumor growth suppression." (PMID 38473779, 2024). "For example, in colorectal cancers overexpressing EGFR, the presence of a strongly activating KRAS mutation eliminates the effectiveness of EGFR-targeting antibodies, even in tumors with highly overexpressed EGFR." (PMID 38639476, 2024). "Mutations in the gene encoding KRAS and BRAF are prevalent in tumors of patients with colorectal cancer." (PMID 38277448, 2024). "The analysis focused on only three genetic mutations (KRAS, BRAF, EGFR), despite colorectal cancer’s complexity with many potential driver mutations." (PMID 39722096, 2024). "The link between KRAS mutations and CIMP‐low status in colorectal carcinoma was discovered in the past." (PMID 39039804, 2024).